CCL19 (C-C motif chemokine ligand 19)
Diseases named in the same sentence as CCL19 in open-access papers (continued):
Sharing a sentence is not in itself a finding about the gene and the disease.
tumor (continued). "We showed a positive correlation between the dose of the CCL19-based APC-targeting TCV and its anti-tumor efficacy, as well as showing the longevity of the neoepitope-specific T cells." (PMID 37720215, 2023). "Cytokine-based signalling pathways, such as the CXCL13/CXCR5 axis and the CCL19,21/CCR7 axis, mediate the recruitment of B cells and TLSs in tumours." (PMID 36890557, 2023). "In another approach, CAR-T cells have been enhanced by dual overexpression of CCL19 and IL-7, with CCL19 here being another ligand of CCR7 which leads to increased migration of endogenous immune cells into the tumor." (PMID 36167831, 2023). "The CCL19 high-expression group displayed higher TIDE scores, indicative of stronger tumor immune function." (PMID 37944262, 2023). "The result showed that these OVs had a similar anti-tumor activity with oHSV2-GM-CSF and oHSV2-IL7 × CCL19 being a litter better than the other three viruses." (PMID 35459242, 2022). "Since the mesoCAR-N19 cells can only release CCL19 in the activated state, we constructed two activation models, namely the coated OKT3 antibody model and the tumor cell stimulation model." (PMID 35990619, 2022). "Simultaneous infection of stromal and tumor cells; Upregulation of Fez1 and Pycard; Downregulation of DLL-4, Angiopoietin 2, PECAM, Tie-1, and FOS EGR2, CREB-5, IL-6, Map2K1, CCL22, TIMD4 and CCL19." (PMID 35640930, 2022). "We found that 47 genes were upregulated in tumor tissues compared to normal tissues, such as CD48, TIGIT, GNLY, CCL19, CCL5, CXCL13, CCL17 and NKG7." (PMID 36713530, 2022). "Recently CCL19/CCR7 axis has been identified to modulate EMT and mediate tumor cell invasion and migration through the AKT signaling pathway in BC48." (PMID 35725915, 2022). "Subsequently, CCL19 expression is restricted inside the tumor tissue, which then promotes memory CAR-T infiltration into the tumor tissue." (PMID 35990619, 2022). "Taken together, these observations indicate that CCL19 and CCL21 inhibit the growth of HCC by enhancing the infiltration of tumor-infiltrating T cells and B cells." (PMID 35673582, 2022). "The TLS-related molecule CXCL13 is associated with good prognosis in HCC patients, and the expression of CCL19 and CCL21 in tumours can promote the anti-tumour effect of TILs." (PMID 36291944, 2022). "It was found that CCL19 expression significantly decreased in CRC, which was closely related to tumor proliferation." (PMID 36581948, 2022). "Differentially expressed cytokines (CCL5, CCL19, CXCL9 and CXCL10) were related to the overall survival, and their expression levels were also examined both in tumor tissues of CL-BCa patients by IHC and in typical CL-BCa cell lines by qPCR." (PMID 35359417, 2022). "In turn, neutrophils secrete numerous chemokines, such as CCL2 (MCP-1) and CCL3 (MIP-1), CCL19, and CCL20, to attract monocytes and dendritic cells into the tumor microenvironment." (PMID 36111233, 2022). "Further, recent studies have shown that TLS promotes recruitment of lymphocytes to the tumor microenvironment by expressing chemokines such as CXCL10, CCL19 and CCL2131." (PMID 35027623, 2022). "generated CCL19-IL-7 CAR-Ts and reported that these cells mediated effective tumoricidal responses in mouse models of solid tumors with enhanced tumor-site trafficking and expansion even in the immunosuppressive TME." (PMID 35634281, 2022). "With this in mind, CAR-Ts engineered to produce CCL19 and IL-7 (CCL19-IL-7 CAR-Ts) can act in a similar fashion as fibroblastic reticular cells in terms of T cell and DC recruitment to the desired tumor sites to help amplify tumoricidal effects." (PMID 35634281, 2022). "In addition to immune cells, the CCR7/CCL19 axis is expressed in airway smooth muscle cells, myofibroblasts, and fibroblasts (Rodríguez-Fernández and Criado-García, 2020), and is involved in biological processes such as tissue repair, endothelial-mesenchymal transition, and tumor metastasis." (PMID 36589450, 2022).
tumor (continued). "Our result (observed upregulation of the CCL19/CCR7 axis on mRNA expression level), in a macroscopically unchanged area surrounding the tumor, confirms the presence of immunological/molecular variations in this tissue." (PMID 35160116, 2022). "Together, the synergic effects of the hub genes, CCL19, CXCL12, and C5AR1, promote chemotaxis, tumour proliferation, and even metastasis, which are in line with previous studies and evidenced by the progressive MCTVT growth." (PMID 34980125, 2022). "Meanwhile, researchers found that the increased expression of CCL19 and CCL21 in tumors can result in infiltration of TILs and an improved prognosis for many tumor patients." (PMID 35065633, 2022). "In mouse CRC models, we demonstrated that all four chemokines, including CCL3, CCL19, CCL21, and XCL1, effectively inhibited tumor growth." (PMID 36654820, 2022). "In both models, tumoral overexpression of CCL3, CCL19, CCL21, and XCL1 significantly repressed tumor growth, despite the differential overexpression levels in these cell lines." (PMID 36654820, 2022). "For example, CCR7 and its ligands (CCL19/CCL21) are a vital axis for carcinogenic properties, such as epithelial-mesenchymal transition, tumor invasion and migration." (PMID 36291815, 2022). "Both types of CAR-Ts overexpressing CCL19 (mesoCAR-CCL9 and mesoCAR-N19) exhibited higher tumor infiltration abilities when compared with those by conventional CAR-T (mesoCAR-T)." (PMID 35990619, 2022). "Except for NOS1, DNMT1 and CCL5, the hub genes CCL19 and CCR7 in DE-GRGs are compose of the CCL19/CCL21-CCR7 axis that exerts both immune response and tumor proliferation." (PMID 35517412, 2022). "The results of tumor purity showed that three cytokines (CCL5, CCL19 and CXCL9) were negatively correlated with tumor purity, which indicated that tumor cells were reduced but immune cells increased in tissues with high expression of these cytokines." (PMID 35359417, 2022). "After the CAR-T cells reach the tumor tissue and are activated by the antigen, the NFAT signaling pathway is then activated and triggers CCL19 expression." (PMID 35990619, 2022). "Herein, anti-CD19 CAR T cells engineered to secret IL-7 and CCL19 are used to treat diffuse large B cell Lymphomas (NCT04381741, NCT04833504), aiming at promoting tumor infiltration, accumulation, and survival of CAR T cells in cancerous tissue." (PMID 36366354, 2022). "It has been reported that the CCL19/CCL21/CCR7 axis functions in immune cells and helps cells migrate to SLOs or other tumor sites and activate the host cell response." (PMID 34689225, 2022). "Four tumor microenvironment-related genes (CD79A, CXCL13, IL6 and CCL19) were identified as biomarkers for PRCC prognosis." (PMID 33993869, 2021). "Compared with those in the normal pancreas (GTEx + TCGA), CA9, TNNT1, CCL21, LY86, and CCL19 were all expressed higher in tumor tissues, except for FABP4, which was expressed lower in a tumor (p < 0.001)." (PMID 34777388, 2021). "Under the chemotaxis of CCL19, CAR-T cells had a significant increase in the degree of tumor tissue infiltration; also, the antitumor effect in vitro was significantly enhanced." (PMID 34527749, 2021). "Consistent with all above the results, immune-related genes were highly expressed in hot tumor, for instance, CXCL9, TCL1A, CCL19, CXCL13, MS4A1, and C4orf7." (PMID 33816503, 2021). "The CAR-T cells engineered to express IL-7 and CCL19 have been validated to increase the infiltration of peripheral CAR-T cells and dendritic cells and into tumor tissues and enhance the anti-tumor immune responses." (PMID 34790207, 2021). "These included IL-12p70, pro-inflammatory IL-1β, and TNF, as well as MIP-3α (CCL20) and MIP-3β (CCL19), which are chemotactic for lymphocytes and DCs, and IFN-α, which is known to activate antigen presentation for T cell-mediated tumor cell recognition." (PMID 34912334, 2021).
tumor (continued). "The tumor tissue continuously expressed CCL19 and analyzed the tumor-suppressive effect of AAV-CCL19 on GPC3 CAR-T by in vitro and in vivo experiments." (PMID 34527749, 2021). "CAFs-3 from the primary tumor showed distinct expression of other chemokines and growth factors, such as C3, CCL5, IGF1, CXCL10, CXCL9, and CXCL14, in addition to CCL19 and IGF2." (PMID 34790166, 2021). "This increases their homing behaviour and drives tumor growth and metastasis, particularly towards lymphatic organs, where the two ligands of CCR7, CCL19 and CCL21, are constitutively expressed." (PMID 34575965, 2021). "This indicates that hypoxia reduces CCL19/ELC and CCL21/SLC protein expression in a tumor but this effect is dependent on the tumor model." (PMID 32781743, 2020). "Chemokine axes such as CCL19, CCL21/CCR7, CCL20/CCR6, CXCL12/CXCR4, and CXCL13/CXCR5 correlate with B cell infiltration to tumor sites." (PMID 31991604, 2020). "In the current study, we also found that especially four chemokines were upregulated in the recurrent tumor compared to the primary tumor; CCL13, CCL18, CCL19, and CXCL14." (PMID 33352957, 2020). "Increased expression of CCL19 and CCL21 in a tumor results in anti-cancer TIL infiltration and an improved prognosis for many tumor patients." (PMID 33076281, 2020). "We also investigated the presence of CXCL12, CCL21, CXCL11, IP-10 (or CXCL10), CCL19, and CCL27, which participate to the recruitment of specific NK cell populations to the tumor site." (PMID 31105699, 2019). "HUVECs were cultured in tumor cell supernatant from SW1116/Vector, SW1116/CCL19, SW620/sh-NC, and SW620/sh-CCL19." (PMID 30250188, 2018). "In conclusion, this study reveal that CCL19 is low-expressed in CRC tissues, which links to highly tumor MVD." (PMID 30250188, 2018). "Our study showed that CCL19 was significantly low-expressed in CRC tissues and positively related to highly tumor microvessel density." (PMID 30250188, 2018). "To identify specific CCL19-regulated miRNAs alterations, we detected the expression of CRC progression-related miRNAs in HUVECs treated by tumor cell supernatants using RT-PCR." (PMID 30250188, 2018). "Various factors, including tumour stroma-released chemokines and cytokines (CCL19 and transforming growth factor-β (TGF-β)), hypoxia, and prostaglandins (PGE2), act as chemoattractants and induce DC recruitment into the tumour microenvironment." (PMID 28913366, 2017). "We observed that the mRNA expression of CCL5 and CCR5 as well as LTβR-related chemokines, such as CCL21, CCL19 and CXCL13 were substantially enhanced in the tumor tissue of EL4-Axl-bearing mice compared with mock control." (PMID 28423548, 2017). "For example, classical chemokines and their cognate receptors CXCL12-CXCR4, CCL19/CCL21-CCR7 and CCL27/CCL28-CCR10 have been reported to promote the metastasis of tumor cells to normal lungs, lymph nodes and skins, respectively." (PMID 27329720, 2016). "All key molecules in the spleen of tumor bearing old hosts (CD2, CD3ε, CCL19, and CCL5) (also been reported to exist in the spleen) leads to immune cell survival and function through increased T-cell survival and activity." (PMID 26497558, 2015). "This surprising increase of T cell activity from spleens of older hosts due to CD2, CD3ε, CCL19, and CCL5 directly has impacted the decrease in tumor growth we observed in our earlier publication." (PMID 26497558, 2015). "It was revealed that the following immune related factors were key factors being commonly up-regulated for old tumor bearing hosts compared to all younger age groups: CD2, CD3ε (or CD3E), CCL19, and CCL5." (PMID 26497558, 2015). "In the immunohistochemical analysis, the significant correlation between HERV-H and CCL19 expressions and accumulation of CD271+ cells (possibly including the HERV-H-induced MSCs) was observed in tumor tissues of colon cancer patients." (PMID 25883937, 2015).
tumor (continued). "In summary, factors regulating TLS formation in epithelial tissues, such as the chemokines CCL19, CCL21 and CXCL13, and the cytokine LTαβ, most likely also contribute to an anti-tumor immune response in several carcinomas/adenocarcinomas." (PMID 24762633, 2014). "Ectopic delivery of LTα/β or LIGHT (aka TNFSF-14 or CD258) promotes PNAd+ HEV, CCL19/CCL21 production, massive naïve T cell infiltration, and (tumor-specific) cross-priming in the context of TLO structures." (PMID 24348473, 2013). "In BC, high CCL19 expression may augment the recruitment of activated CD8 T cells to the tumor microenvironment, enhancing immune surveillance and tumor cell eradication." (PMID 40895068, 2025). "Notably, there was a significant increase in the expression of the chemokines CCL19 and CCL21 at the tumor site, especially in the M-HIFU-treated group." (PMID 39861713, 2025). "Early phase clinical trials of dual IL-7 and CCL19-armored CAR T-cell have reported preliminary evidence of anti-tumor activity and no grade >2 toxicities, although further studies will be needed to confirm clinical benefit." (PMID 41019052, 2025). "Therefore, it became imperative to employ vectors for delivering CCL19 into the TME, allowing for its stable expression within tumor tissues and the provision of long-term anti-tumor effect." (PMID 41446741, 2025). "Thus intratumoral over-expression of CCL19 emerged as an effective strategy to remodel TME, furthermore, inhibiting tumor growth and metastasis." (PMID 41446741, 2025). "We previously reported NECTIN-4 CAR-T cells co-expressing IL-7 and CCL-19 displayed significant anti-tumor activity in vitro and in vivo without obvious on-target off-tumor toxicities." (PMID 39735536, 2024). "Consistent with the previous understanding that tumour‐derived CCL19 inhibited the CD8 T cell and promoted lymph node metastasis, we hypothesize NPC tumour cells will release CCL19 and reshape the immunosuppressive TIME of metastatic lymph nodes via CCR7." (PMID 39392128, 2024). "increased the expression of CCL19, CCL21, CXCL10, and CXCL13 through activation of the LT-α and LT-β pathways, promoting TLS formation, enhancing the local immune response, and delaying tumor growth." (PMID 39840050, 2024). "Similarly, the expression of IL-7 and CCL19 in CAR-GPC3 T cells can promote T cell survival and tumor infiltration, leading to stronger tumor suppression compared to traditional CAR-T cells in xenograft and PDX models." (PMID 38679698, 2024). "The heatmap showed significant differential expression of genes such as HSPA9, CCL19, and CD247 in cluster B, which may implicate their roles in tumor progression." (PMID 38312844, 2024). "Recently, CCL19/21 have been shown to induce the migration of CD4+ T cells to non-lymphoid tissue, especially to the nervous system, to preserve the balance between immune surveillance (against tumor and pathogens) and tolerance." (PMID 38330029, 2024). "Notably, CCL19 has been found to enhance CD8+ T cell responses, thereby aiding the immune system in effectively targeting and eliminating tumor cells." (PMID 39505867, 2024). "As a first step, we set forth to verify that the observed reduction in CCL19 and CCL21 in healthy mice was also present in B16F10-Luc tumor-bearing mice treated with the treatment regimens used throughout this study (“TM IR + ICI”, “TM + C-DLN IR + ICI” and “TM + NEO-DLN IR + ICI”)." (PMID 38951172, 2024). "The CCL19/21-CCR7 axis can be used to promote NK cell infiltration, and chemokine receptor CCR7-bearing NK cells genetically reprogrammed by cGMP-compliant mRNA electroporation method showed enhanced migratory ability towards their ligands CCL-19 and CCL-21 and offered tumor infiltration." (PMID 36797756, 2023). "On the one hand, we found that CCR7 was highly expressed in tumor samples in the TCGA database (p < 0.05), while the difference in CCL19 was not statistically significant (p = 0.328)." (PMID 37864213, 2023).
tumor (continued). "Using the chemokine CCL19, we designed an APC-targeting pDNA vaccine, CCL19_Neo13, capable of inducing dose-dependent, robust, and long-lasting cellular immune responses, and anti-tumor efficacy." (PMID 37720215, 2023). "Finally, we show that administration of the CCL19-based APC-targeting TCV post-tumor inoculation, can achieve tumor control as a monotherapy." (PMID 37720215, 2023). "Notably, mregDCs express CCL17, CCL19 and CCL22,26, 27 which promote Treg migration into the TME by binding to CCR4 and promoting tumour invasion and drug resistance to immune checkpoint blockade (ICB) treatment." (PMID 36808888, 2023). "Besides, inducing tumor cells to overexpress CCL19 or CCL21 by transfection also enhances the functions of DCs and tumor control." (PMID 38008741, 2023). "However, the function of the CCL19, CCL21/CCR7 and CXCL13/CXCR5 axes in tumor immunity is complicated." (PMID 37215990, 2023). "Furthermore, the highly expressed DEGs of fibroblasts in LNM included immune-related genes (CCL21, CCL19, CCL2, and MYC), metabolism-related genes (STEAP4, FABP4, DPT, and APOE), and genes related to tumor proliferation and progression (RGS, CCN, and MYC)." (PMID 37221625, 2023). "LAMP3+DC highly expresses chemokine CCL19 and its receptor CCR7, which may recruit other immune cells to migrate to tumor tissues through the CCL19-CCR7 axis." (PMID 37675100, 2023). "Interestingly, anti-tumor immune cells, specifically the CD8+ T cells and macrophages, were clustered from TME by elevated CCL19 expression." (PMID 37944262, 2023). "Overall, our results suggest that the establishment of an effective tumor-killing environment composed of favorable cell types, such as DCs, CD8+ memory T-cells, and NK cells, as well as important chemokines, including CCL19, CXCL10, and XCL1 relies on all aspects of the combination therapy." (PMID 36741387, 2022). "However, if located on cancer cells, CCR7 and its ligands (CCL19/CCL21) is a vital axis for carcinogenic properties, such as epithelial-mesenchymal transition (EMT) tumor invasion and migration." (PMID 35938006, 2022). "In serum of CT26 tumor-bearing mice, there was extensive overlap with the factors detected in CT26-conditioned media: following mediators identified in conditioned media showed at least a 1.2-fold increase in CT26 tumor-bearing mice: IL-1α, IL-2, IL-13, CCL2/5/19, LIX, CX3CL1, CXCL1/2/10 and CCL19." (PMID 35962398, 2022). "Interestingly, secretion of CCL19 recruited not only T cells, but via their receptor CCR7 also DCs, aiding T cell priming and activation within the tumor as well as infiltration." (PMID 36366354, 2022). "On day 24 after treatment, mice treated with 5voHSV2 had an average tumor volume of 362 mm3, while the average tumor volume of mice inoculated with OVs was 1 450 mm3 (oHSV2-IL12), 1 711 mm3 (oHSV2-PD1v), 951 mm3 (oHSV2-IL7 × CCL19), 893 mm3 (oHSV2-GM-CSF) and 1 443 mm3 (oHSV2-IL15)." (PMID 35459242, 2022). "The presence of CCL19 in mesoCAR cells did not affect their mesothelin-positive tumor cell Aspc-1 killing activity over 4 h." (PMID 35990619, 2022). "In addition, CCL19-expressing chimeric antigen receptor (CAR) T cells promoted the infiltration of DCs and T cells into tumor tissues and exerted synergistic anti-tumor activity with recipient immune cells." (PMID 35550569, 2022). "The transcriptional levels of 5 chemokines (CXCR5, CXCL12, CXCL13, CCL19, and CCL21) that have been reported to be involved in the formation of TLSs were also prominently elevated in both the tumor specimens from mIgG2c-G400R mice and hIgG1-G396R homozygous CRC patients." (PMID 35133976, 2022). "CCL19 binds to CCR7 on a multitude of cell types including DCs and T-cells, whereas CXCL10 is a is a canonical chemokine for attracting T-cells, and its upregulation is correlated with smaller tumor size." (PMID 36741387, 2022).